MIR4527 (microRNA 4527)
Synonyms: hsa-mir-4527
Gene: MicroRNA gene on chromosome 18 (47,380,496 to 47,380,565, forward strand). Ensembl gene ENSG00000266582.
Homologues: Orthologues: chimpanzee MIR4527 (100% identical).